CD200 (CD200 molecule)
Diseases named in the same sentence as CD200 in open-access papers (continued):
Sharing a sentence is not in itself a finding about the gene and the disease.
psoriasis vulgaris (1 paper, 2020). Plaque psoriasis is the most common presentation of psoriasis. "In conclusion, abnormalities in the expression of elements of the CD200/CD200R axis have been detected in psoriasis vulgaris patients in the form of peripheral overexpression of the ligand and down-regulation of the receptor when compared to normal controls." (PMID 32203537, 2020). "The current study aimed to investigate the status of the CD200/CD200R axis in the blood of psoriasis vulgaris patients versus healthy controls." (PMID 32203537, 2020). "Both findings collectively indicate that CD200 or CD200R peripheral expression levels cannot serve as markers of disease severity in psoriasis vulgaris." (PMID 32203537, 2020). "Aberrant expression of CD200/CD200R might play a role in psoriasis vulgaris pathophysiology and disease severity." (PMID 32203537, 2020).
rectal cancer (1 paper, 2019). A primary or metastatic malignant neoplasm that affects the rectum. "Our findings also suggest the extension of the therapeutic use of CD200:CD200R1 blockers to rectal cancer patients that might lead to the more effective treatment modalities." (PMID 30800162, 2019). "We examined the immunohistochemical expressions and localizations of CD200 and CD200R1 in 140 rectal cancer patients." (PMID 30800162, 2019). "Our aim was to investigate the expression and localization of CD200 and its receptor CD200R1 and their clinical significance in rectal cancer patients." (PMID 30800162, 2019). "In conclusion, we have identified CD200 and its receptor CD200R1 expression profiles and their location in tumor and tumor surrounding is, for the first time, demonstrated in rectal cancer patients." (PMID 30800162, 2019). "Because of the long follow-up time together with the different treatment modalities used and other clinical data in our large study group, we determined the correlations and clinical importance of CD200:CD200R1 receptor profile and their location of expression in rectal cancer patients." (PMID 30800162, 2019).
Richter syndrome (1 paper, 2016). Transformation of chronic lymphocytic leukemia into aggressive non-Hodgkin's lymphoma, usually diffuse large B-cell lymphoma (immunoblastic or centroblastic variant). "In cases with CD200 MFI < 198.5, 7/152 (4.6%) patients transformed to Richter syndrome (RS), while 2/155 (1.3%) patients transformed to RS in cases with CD200 MFI ≥ 198.5 (odds ratio: 3.70, 95% CI: 0.85–18.08, p = 0.1015)." (PMID 26910908, 2016).
sensitization (1 paper, 2024). "The profile of cDC2 subsets in the lung changes during allergic sensitization, as Ly6C+ inflammatory cDC2s are recruited to the lung and CD200+ cDC2s undergo expansion." (PMID 38883724, 2024). "Single cell RNA sequencing and adoptive transfer experiments show that during allergic sensitization, many CD301b+ cDC2s transition in a stepwise manner to CD200+ cDC2s that selectively promote Th2 differentiation." (PMID 38883724, 2024).
skin squamous cell carcinoma (1 paper, 2025). A carcinoma arising from the squamous cells of the epidermis. "One study found that CD200/CD200R signal transduction promotes skin squamous cell carcinoma invasion and metastasis through ctsk expression." (PMID 40718780, 2025).
spina bifida (1 paper, 2018). A congenital neural tube defect in which vertebrae are not fully formed. "The relationship between the imbalance of CD200-CD200R and the pro-inflammatory cytokines in spina bifida was demonstrated by the expression of the ligand CD200, mostly by neurons, and the expression of receptor CD200R, mostly by microglia." (PMID 30006626, 2018).
staphylococcal infection (1 paper, 2019). An infection caused by Staphylococcus. "To explore the mechanism underlying the immunosuppressive effects of CD200 on macrophages, we detected the effects of CD200 siRNA on NF-κB activation in response to Staphylococcal infection." (PMID 30717437, 2019). "The result showed that Staphylococcal infection induced the expression of CD200 in a dose-dependent manner." (PMID 30717437, 2019). "Furthermore, our data demonstrated that p38 mitogen-activated protein kinase (MAPK) was selectively down-regulated by CD200 administration, while enhanced upon CD200 silence in response to staphylococcal infection." (PMID 30717437, 2019). "To further substantiate the effect of CD200 on S. aureus-triggered inflammatory responses, we then transfected mouse PEMs with CD200-targeted or non-specific (NC) siRNA, followed by Staphylococcal infection." (PMID 30717437, 2019).
synovitis (1 paper, 2019). Inflammation of a synovial membrane. "In this study, IFP tissue was obtained from non-arthritic patients undergoing elective arthroscopy in whom active inflammation (i. e. synovitis) was ruled out by MRI, consistent with the low CD200 expression levels in naïve IFP-MSC." (PMID 31350444, 2019).
tonsil carcinoma (1 paper, 2019). A carcinoma that involves the tonsil. "As CD200 plays a critical role in immune cells, and as cancer cell metastasis involves the function of several immune cells, we further investigated the role(s) of CD200 during EMT of MEER cells established as a murine HPV+ tonsil carcinoma model." (PMID 31627350, 2019).
tonsillar squamous cell carcinoma (1 paper, 2019). A squamous cell carcinoma that arises from the mucosal lining of the tonsil and tends to metastasize early to the lymph nodes. "CD200 increased the invasiveness of mouse tonsillar epithelium immortalized with E6, E7, and Ras (MEER), a model of tonsillar squamous cell carcinoma." (PMID 31627350, 2019).
uveal cancer (1 paper, 2019). A primary or metastatic malignant neoplasm that affects the choroid, ciliary body, or iris. "Also, most of the inhibitory immune-checkpoints analyzed were not different in uveal cancer, with the exception of CD200 and HVEM, that resulted significantly reduced." (PMID 30653520, 2019).
tumor (159 papers, 2010 to 2026). "The expression levels of immune checkpoints, including BTLA, VTCN1, CD276, PDCD1, CD160, NRP2, and CD200, as well as the tumor-associated fibroblast marker FAP, were found to be higher in the high-risk group." (PMID 40364849, 2025). "They found that CD200 overexpression in the host was associated with diminished primary tumor growth and metastasis, while loss of CD200R1 expression by host cells was linked to increased visceral metastasis." (PMID 40075669, 2025). "Nevertheless, the current study also suggests anti-tumor functions associated with CD200/CD200R pathway." (PMID 40718780, 2025). "Overexpression of CD200 has been associated with differential outcomes, depending on the tumor type." (PMID 38619621, 2024). "Studies in multiple myeloma show that tumor cells co-cultured with primary T cells are more likely to survive when expressing CD200, which is also associated with increased Treg levels and reduction in T cell effector function." (PMID 39409893, 2024). "CD200 is highly expressed on tumor cells, impairs antitumor immune responses, and is associated with poor prognosis." (PMID 38745652, 2024). "One mechanism for this immune suppression is that the expression of CD200 on tumor cells enhances the release of IL-10 by tumor-associated myeloid cells, contributes to immune suppression and favors tumor progression and recurrence." (PMID 39795972, 2024). "After describing the association between CD24 and CD200 expression and tumor progression, we conducted a detailed exploration into the immunosuppressive effects of these molecules." (PMID 37894750, 2023). "Some studies showed that activation of CD200R, either by binding of the ligand CD200 or through treatment with an agonistic antibody, leads to inhibition of tumour-associated myeloid cells (TAMCs), ultimately reducing tumour burden." (PMID 37082107, 2023). "Our emphasis was on illustrating how CD24 and CD200 act as signaling checkpoints by engaging their respective receptors, namely, Siglec-10 and CD200 receptor, which are expressed on tumor-associated myeloid cells." (PMID 37894750, 2023). "Increased CD200 expression on tumor cells is associated with tumor progression and decreased patient survival." (PMID 36793738, 2023). "Continued research into the underlying mechanisms through which CD200 influences immune responses and tumor progression is essential." (PMID 38137547, 2023). "CD200’s ability to modulate inflammatory responses, influence the expansion of tumor-associated myeloid cells, and regulate T cell functions underscores its significance in the context of cancer biology." (PMID 38137547, 2023). "A study conducted in the early 2000s demonstrated that CD200 is associated with immune rejection of leukemic tumor cells." (PMID 37894750, 2023). "Expression of CD200 as a surface antigen on tumor cells of myeloid/lymphoid origin has been associated with a poor prognosis in a number of human hematological malignancies." (PMID 33562512, 2021). "We recently provided a model to explain the differential tumor growth in CD200/CD200R-deficient mice among different tumor models." (PMID 34692697, 2021). "In AML patients, NK cell anti-tumor responses were suppressed by the overexpression of CD200, thereby increasing risk for relapse in these patients." (PMID 32117298, 2020). "Overall, in the TCGA dataset, CD200 expression was closely associated with tumor grade, which is considered a marker of the extent of malignant growth." (PMID 31627350, 2019). "A hypothetical model suggested that the overexpression of CD200 is associated with inhibition of tumor-specific immunity by switching the cytokine profiles from T-helper 1 cells (Th1) to T-helper 2 cells." (PMID 30800162, 2019). "Expression of CD200 on tumor cells has been associated with impaired NK cell function, increased frequencies of Tregs, suppression of memory T cells, decreased CTL activity, and induction of tolerance to allografts." (PMID 28515726, 2017).
tumor (continued). "It must however be noted that expression of CD200 is thought to have links to anti-tumor effects by inhibiting activity of tumor-associated myeloid cells via IL-10, arguing caution in targeting a molecule with potentially pleiotropic effects." (PMID 27462861, 2016). "We previously demonstrated that tumor expression of CD200 inhibits the functions of tumor associated myeloid cells and permits better tumor eradication by CTL." (PMID 22319630, 2012). "Our recent study has revealed that tumor expression of CD200 has a direct effect on tumor associated myeloid cells (TAMCs)." (PMID 22319630, 2012). "Although numerous studies have demonstrated that CD200 is upregulated in various types of cancer and is associated with immunosuppression, there is also evidence indicating that CD200 may exert anti-tumor effects." (PMID 40534859, 2025). "In addition, JAM3 was associated with the CD200, an inhibitory immune checkpoint that suppressed anti-tumor immune function by binding its receptor CD200R on myeloid cells." (PMID 38400838, 2024). "The tumor environment, including mechanisms associated with CD200, may determine the extent of immune suppression occurring from vaccines in preclinical studies." (PMID 39795972, 2024). "Thus, this paradigm has found CD200 to be a promising treatment target and also a biomarker across diverse types of cancers, given that high levels of this protein are associated with tumor growth." (PMID 39795972, 2024). "CD24 and CD200 are overexpressed across diverse cancer types and serve as signaling checkpoints by engaging their respective receptors, Siglec-10 and CD200 receptor, which are expressed on tumor-associated myeloid cells." (PMID 37894750, 2023). "The LN-derived tumor cells expressed higher levels of costimulatory and adhesion molecules as well as molecules associated with B-cell activation, including Ki67, PD-1, CD200, and CD47." (PMID 36922932, 2022). "Since we observed increased Tregs in TME of CD200R-deficient tumors, we also examined if anti-CD200 could inhibit tumor growth in combination with anti-CTLA4 antibody 9H10." (PMID 34692697, 2021). "Alternatively, CD200 may induce a conformational change in other associated molecules, resulting in pro-apoptotic signal transduction in tumor cells." (PMID 28429795, 2017). "Consistent with this hypothesis, CD200-expressing tumour cells inhibit CD200R-expressing tumour-associated macrophages, resulting in decreased tumour growth." (PMID 27731341, 2016). "Furthermore, decreased tumor growth in Cd200−/− mice was associated with a shift in the regulatory T lymphocyte/T effector cell balance." (PMID 24897500, 2014). "Indeed, the livers of these CD200R1-deficient mice exhibited increased metastatic CD200+ tumor growth which contained higher numbers of CD11b+Ly6C+ myeloid cells, displayed VEGF and HIF1a gene expression with increased angiogenesis, and showed significantly reduced CD4+ and CD8+ T cell infiltration." (PMID 32635224, 2020). "CD200 expression was higher on tumor cells, while CD200R was enriched on lymphocytes, particularly CD8+ T cells." (PMID 42273703, 2026). "Equal numbers of Cd200+ primary tumor cells were seeded into 3D 96-well plates and cultured on Matrigel." (PMID 41597281, 2026). "Further, KLF4-ChiP assays of the CD200 promoter in D2A1 tumor cells with KLF4 overexpression revealed that KLF4 protein was enriched at −200~+30bp region of the CD200 promoter." (PMID 40568095, 2025). "CD200R1 is a member of immunosuppressive receptors principally expressed in immune cells such as CD4+/CD8+ T cells and myeloid cells, while its ligand CD200 is present in various normal and tumor cells." (PMID 40936767, 2025). "Blockade of CD200/CD200R interactions using monoclonal antibodies like samalizumab has shown promise in restoring anti-tumor immunity, particularly in hematologic malignancies." (PMID 40075669, 2025).
tumor (continued). "The binding of CD200 on tumor cells with its receptor, CD200R, expressed on macrophages, DCs and T lymphocytes, delivers negative signals that promote immune tolerance." (PMID 41233805, 2025). "In turn, overexpression of CD200R on B cells and CD200 on T cells indicates further mechanisms promoting immune tolerance and evasion of immune surveillance by tumor cells." (PMID 40355604, 2025). "Tumor tissue from 21 participants (75%) contained an adequate number of tumor cells to be evaluable for expression of CD200, and 12 of the 21 (57%) had detectable tumor cell CD200 expression (CD200 H-score > 0, assay range 0–300)." (PMID 39651931, 2025). "The PK/PD data from this study provide evidence for maximal CD200/R1 blockade with 23ME-00610, peripherally and potentially in the tumor." (PMID 39651931, 2025). "Based on nonclinical studies, 23ME-00610 leads to restoration of immune cell activity, including in T cells, and mediates immune cell killing of CD200-expressing tumor cells." (PMID 39651931, 2025). "An analysis of these immune checkpoints in tumor and normal samples revealed significant differences in the expression of CD200, CD274, TIGIT, TNFRSF25, and TNFSF15 between the two groups (P < 0.05)." (PMID 40666524, 2025). "CD200 is also highly expressed on tumor cells and some stromal cells in the tumor microenvironment in several hematologic and solid tumor malignancies." (PMID 39651931, 2025). "Future studies that investigate how CD200 modulates immune responses and tumor progression in MCC would offer deeper insights." (PMID 40075669, 2025). "While the CD200-CD200R axis is known to deliver inhibitory signals that weaken antigen-presenting cell and T cell activity, our findings align with emerging evidence that CD200 can also exert tumor-restraining effects." (PMID 41488652, 2025). "In parallel, CD4+/CD8+ CXCR5+T follicular helper cells and CD8+CD103+ tissue-resident memory T cells were observed infiltrating in tumor tissues, Moreover, CD200 expressing B (CD20+CD200+) and T cells (CXCR5+CD200+) accumulated in the DCB groups." (PMID 40404633, 2025). "Our experiments are in part consistent with the majority of research finding that CD200 expression on human cancer cells is thought to have a pro-tumor effect in cancer development." (PMID 40718780, 2025). "In NSCLC, Cluster of Differentiation 200 (CD200)-expressing CAFs have been found to increase tumor cell sensitivity to targeted therapies, such as Epidermal Growth Factor Receptor (EGFR) inhibitors, and this effect disappears when CD200 is absent." (PMID 40940809, 2025). "The participant with a RECIST-confirmed PR had detectable CD200 (with 100% tumor cell expression CD200) and the highest H-score observed in evaluable participant data." (PMID 39651931, 2025). "Among the immune checkpoints, the CD200 cell surface glycoprotein has gained attention for its role in promoting self-tolerance and potentially facilitating tumor growth through interaction with the CD200R1 receptor." (PMID 40904466, 2025). "Tumor cells expressing CD200 can suppress macrophage and dendritic cell activation, reduce T-cell cytotoxicity, and foster an immunosuppressive tumor microenvironment." (PMID 40075669, 2025). "Upon anti-CD200 antibody treatment, the Th1 response was restored, thus suggesting the tumor-inducing property of CD200." (PMID 37605389, 2024). "One of the major challenges involves the delivery of such therapeutics against CD200 into the tumor microenvironment." (PMID 39795972, 2024). "Recently, a CD200R1-targeting antibody, 23ME-00610, was reported to enhance the function of anti-tumor T cells by blocking CD200:CD200R1 binding, thus inhibiting tumor growth while participating in the immune activation pathway." (PMID 38903709, 2024). "Ultimately, these results indicate that CD200 is overexpressed by tumor, stromal cells, and immune populations in the PDAC TME, and that CD200 expression is not dependent on pathology grade or cancer stage." (PMID 38619621, 2024).